LINC01281 (long independently transcribed non-coding RNA 1281)
Gene: Long non-coding RNA gene on chromosome X (39,304,956 to 39,327,423, reverse strand). Ensembl gene ENSG00000235304.
Diseases named in the same sentence as LINC01281 in open-access papers:
LINC01281 is named in the same sentence as 2 diseases in open-access papers, as found by Europe PMC text mining. Sharing a sentence is not in itself a finding about the gene and the disease. The quoted sentences say what the papers report.
laryngeal carcinoma (1 paper, 2022). Carcinoma that arises from the laryngeal epithelium. "In addition, LINC01281 is considered a protective factor for laryngeal cancer." (PMID 36330457, 2022).
LINC01281 also shares sentences with these, for which no sentence is quoted: cancer (1 paper).